AHR (aryl hydrocarbon receptor)
Diseases named in the same sentence as AHR in open-access papers (continued):
Sharing a sentence is not in itself a finding about the gene and the disease.
Autoimmunity (62 papers, 2010 to 2026). The occurrence of an immune reaction against the organism's own cells or tissues. "We identified a potential involvement of the faecal tryptophan metabolite indole-3-lactic acid (ILA) produced by lactobacilli, which is implicated in the suppression of CNS autoimmunity via aryl hydrocarbon receptor (AHR) activation." (PMID 40359627, 2025). "In contrast, in B regulatory cells, AhR appears necessary for optimal production of IL-10, as AhR deficiency in this cell population drove autoimmunity and differentiation of pro-inflammatory B cells." (PMID 39474416, 2024). "Some studies showed that AhR-deficient mice are prone to autoimmunity, whereas AhR-responsive mouse strains with constitutive expression of the AhR have been shown to be more susceptible to developing malignancies." (PMID 29487603, 2018). "Additionally, dioxins and BPA activate the aryl hydrocarbon receptor (AHR) and NF-κB pathways, enhancing IL-6 and IL-1β expression, which promotes Th17 responses associated with autoimmunity." (PMID 41020825, 2025). "Moreover, polycyclic aromatic hydrocarbons, smoking, air pollution, and other environmental exposures cause DNA methylation changes in the AHR repressor genes, potentially linking these exposures to the development of autoimmunity." (PMID 39318630, 2024). "Since the discovery that AHR-deficient mice are prone to autoimmunity and that mice expressing a constitutively active AHR are prone to develop tumors, it has been speculated that endogenous TRP metabolites are responsible for inducing AHR-mediated tolerance." (PMID 25628622, 2014). "By stimulating the aryl hydrocarbon receptor (AhR), Lactobacillus reuteri metabolize tryptophan to boost CNS autoimmunity and IL-17 production." (PMID 39934561, 2025). "Pollutants can activate aryl hydrocarbon receptor (AhR) promoting Th17-mediated inflammation and suppressing regulatory T cell (Treg) function exacerbating autoimmunity and chronic inflammation." (PMID 41425557, 2025). "Future studies are warranted to elucidate the pathways by which regulation of the AHR pathway is related to lymphocyte activation status in the pathogenesis of autoimmunity." (PMID 39318630, 2024). "Estrogen has also been found to regulate the immune system and contribute to the transduction pathways of autoimmunity by activating its nuclear receptor AhR." (PMID 38395801, 2024). "AHR’s ubiquitous expression in barrier tissues coupled with its complex ligand-binding profile warrants further study of AHR function in autoimmunity." (PMID 36787309, 2023). "Given the emerging role of the microbiome and the well-accepted contribution of T cells to MS pathology, AHR is ideally positioned to influence CNS autoimmunity." (PMID 36787309, 2023). "The induction of Th17 and autoantibodies by E. gallinarum was eliminated by the administration of a selective AhR antagonist, which indicates that E. gallinarum promotes autoimmunity by AhR signaling." (PMID 37533870, 2023). "Another regulator QKI alters inflammation by downstream regulation of the AHR and NFκB signalling and as such, similar to the Fox genes can also regulate autoimmunity." (PMID 35328504, 2022). "AHR has been identified as an important regulator of the immune response in autoimmunity, cancer, and infections." (PMID 34446714, 2021). "In the last decade, AHR has been shown to play a critical role in many alternative pathways like autoimmunity, metabolic imbalance, inflammatory skin, gastro-intestinal disease among others." (PMID 33203443, 2020). "It is now of key interest to examine the potential involvement of FICZ, a major physiological activator of the AHR, in inflammatory disorders and autoimmunity." (PMID 32784381, 2020). "Recent reports suggest that activation of aryl hydrocarbon receptor (AhR) signals by various ligands such as tryptophan derivatives can induce hyper-immune responses and are involved in autoimmunity." (PMID 32033616, 2020).
Autoimmunity (continued). "In summary, we demonstrate that the NK cell-activating functions of the AhR can be used to suppress CNS autoimmunity and improve anti-tumor immunity." (PMID 30808363, 2019). "In the present study, we report that the AhR-mediated activation of NK cells augments anti-tumor immunity and is relevant for maintaining the efficacy of laquinimod to ameliorate CNS autoimmunity." (PMID 30808363, 2019). "To assess the functional relevance of AHR regulation during the TH17 cell-mediated autoimmunity, we further inhibited AHR activity during the development of EAE by using a specific antagonist (CH223191)." (PMID 30425241, 2018). "Similar to the VDR, other nuclear receptors, such as the aryl hydrocarbon receptor, also regulate intestinal microbiome, enhance barrier integrity, reduce inflammation and autoimmunity, and increases disease tolerance." (PMID 30828578, 2018). "More specifically, PAHs present in DEPs and their OFs enhance effector T cell differentiation via the AHR and lead to worsened autoimmunity." (PMID 30143013, 2018). "Both models indicate a therapeutic effect of AhR activation in autoimmunity development in adult animals." (PMID 25883945, 2015). "In agreement with this, in another murine model for autoimmunity, systemic lupus erythematosus (SLE), TCDD appears to promote differentiation of regulatory T-cells via AhR and inhibiting Th17 cells and cause immunosuppressive effects." (PMID 25883945, 2015). "Because the balance between Treg and Th17 cells is now considered to be more important than the Th1/Th2 balance in regard to the onset of autoimmunity, AHR has attracted increased attention in the context of immunology." (PMID 25400638, 2014). "In contrast to the role that the AHR plays in regulating autoimmunity when presented with endogenous ligands, at interface organs such as the lung, gut, and skin, AHR activation leads to an effector response." (PMID 25324842, 2014). "As we better understand the mechanisms and signals behind the role of the AHR in the immune system, we will be able to manipulate this receptor to treat or prevent diseases as diverse as cancer, autoimmunity, and transplant rejection." (PMID 25324842, 2014). "Aromatic hydrocarbons and non-halogenated polycyclic aromatic hydrocarbons also induce differentiation of Th17 cells through binding at the Aryl hydrocarbon Receptor (AhR), exacerbating autoimmunity." (PMID 25196523, 2014). "The relationship of the endogenous ligand kynurenine and the AHR allows a feedback loop that dampens an immune response to prevent too much inflammation and autoimmunity, allowing a response to be self-limited." (PMID 25324842, 2014). "Further understanding of the molecular mechanisms responsible for pathologic Th17 differentiation and autoimmunity seen after exposure to pollution will allow direct targeting of proteins involved in AHR activation and function for treatment of PM exposures." (PMID 24349309, 2013). "At the same time, we have already discussed a role for the AHR in the pathogenesis of both autoimmunity and organ rejection." (PMID 22970246, 2012). "In SLE, deficits in the AHR-driven immunoregulation exacerbated by the type-1 IFN may explain how alterations in the environment lead to the development of autoimmunity and uncontrolled inflammation." (PMID 39318630, 2024). "Impaired AHR activation caused by a lack of gut bacterial metabolism of dietary Trp is considered to result in chronic tissue inflammation and autoimmunity." (PMID 37394584, 2023). "There is consensus that AHR is critical for controlling tissue inflammation and autoimmunity." (PMID 37394584, 2023). "For example, there is evidence that the adverse effects of polycyclic aromatic hydrocarbons in PM2.5 are mediated by activation of the aryl hydrocarbon receptor and may lead to autoimmune conditions." (PMID 36311636, 2022).
Autoimmunity (continued). "Importantly, in the EAE model, AhR activation can modulate CNS autoimmunity in divergent directions in a ligand-specific fashion, with FICZ exacerbating disease and TCDD and tryptamine ameliorating disease." (PMID 36419205, 2022). "In addition to the “intestinal barrier – metabolic inflammation,” “SCFA-GPR,” “BAs-FXR,” and autoimmunity have attracted much attention, AhR, AMPK and PPAR-γwere becoming research hotspots in recent years." (PMID 36246235, 2022). "The translocation of a commensal bacterium, Enterococcus gallinarum, from the small intestine to the liver in mice prone to autoimmunity, resulted in a systemic type I interferon signature and anti-dsDNA antibodies production through activation of the aryl hydrocarbon receptor (AhR) system." (PMID 35742974, 2022). "In summary, our results indicate that the AhR-dependent activation of NK cells might be utilized to suppress CNS autoimmunity by decreasing the immunogenicity of CD155+ DCs." (PMID 30808363, 2019). "Summary of the effects of PM and AHR agonists on autoimmunity." (PMID 30574142, 2018). "We tested the hypothesis that the PAHs present in two DEP source samples and their derivative OFs would enhance effector T cell differentiation and aggravate autoimmunity after inhalation via the AHR pathway." (PMID 30143013, 2018). "Additionally, AHR activation by FICZ can exacerbate in vivo TH17 cell-mediated autoimmunity, such as experimental autoimmune encephalomyelitis (EAE) and collagen-induced arthritis." (PMID 30425241, 2018). "Interestingly, ligand-based activation of the NR aryl hydrocarbon receptor (AHR) induces Treg that suppress CNS autoimmunity in EAE by a TGF-β1-dependent mechanism." (PMID 28926619, 2017). "First, we will discuss the possibility that the AHR can be considered as a target for immune modulation and treatment of diseases including autoimmunity and transplant rejection, and paradoxically, also potentially for cancer therapy depending on the ligand employed." (PMID 22970246, 2012). "Recent evidence from studies to control autoimmunity and graft-versus-host disease indicate that the objective might be achieved by the administration of stable agonists of the aryl hydrocarbon receptor (AhR)." (PMID 22174686, 2011). "The direct impacts of the AhR and TrkB on mitochondrial function and how these two receptors interface with the mitochondrial melatonergic pathway should better clarify, and further highlight, the roles of mitochondrial function and their intercellular interactions in the course of ‘autoimmunity’." (PMID 37174637, 2023). "Therefore, although its functions have not been completely understood, NCOA7 may contribute to immunoregulatory mechanisms that can be either pathogenetic (i.e., in neoplasia) or protective (i.e., in autoimmunity), similarly to AhR." (PMID 31481962, 2019). "Because T cell-mediated autoimmunity and altered cytokines are involved in vitiligo as well as AHR plays a pivotal role in T cell development and cytokine production, mutation or abnormal expression of AHR may influence cytokine levels associated with vitiligo." (PMID 26370050, 2015). "Recently, a critical role for the AhR in development of T cells involved in autoimmunity (Th17 and Treg) has been demonstrated, supporting the hypothesis that the AhR plays a key role in immune regulation both in the presence and absence of environmental ligands." (PMID 20334656, 2010). "Recently, AhR–TGF-β1/Smad signaling has been shown to mediate immune suppression in scurfy mice, a mouse autoimmune model." (PMID 35397616, 2022). "Evidence from studies to control autoimmunity and graft-vs.-host disease, even virus induced inflammatory lesions indicate that the regulation of the immune response to avoid immunopathology could be achieved by the administration of the stable agonist of AhR, TCDD." (PMID 30984194, 2019).
Autoimmunity (continued). "Still, our results clearly suggest the presence of an AHR-independent, microbiota-mediated DTR mechanism, which suppresses distant autoimmunity in the CNS." (PMID 31653831, 2019). "Aryl hydrocarbon receptor (AhR) ligands have been demonstrated to influence microglial state during CNS autoimmunity, but their effects under homeostatic conditions have not been reported." (PMID 36151874, 2022). "Although AHR activation can exacerbate in vivo TH17 cell-mediated autoimmunity, accumulating data indicate that AHR is a nonpathogenic TH17 marker." (PMID 30425241, 2018). "Modulating AhR by TCDD has also been shown to control the differentiation of Type 1 regulatory T cells (Tr1) in vitro, which produce IL-10 and are instrumental in the prevention of tissue inflammation, autoimmunity as well as GVHD." (PMID 22174686, 2011). "The interplay between AHR and IRF4 in the regulation of Tr1 cells underscores a complex mechanism that may be disrupted in T1DM, potentially resulting in compromised immune regulation and the onset of autoimmunity." (PMID 39211721, 2024). "The lower AHR expression in T1DM patients could indicate a compromised ability to promote Tr1 cell differentiation and function, potentially weakening a crucial protective mechanism against autoimmunity." (PMID 39211721, 2024). "This, however, stands in stark contrast to an activation of AHR signaling by either FICZ (see UV Radiation-Induced Immunosuppression) or airborne PAHs and PAH-rich PM (see AHR and PAH-Induced Immune Reactions) which stimulate the generation of Th17 cells and exacerbate autoimmune disorders." (PMID 35311158, 2022). "AhR-activation by the AhR ligand drug VAF347 shifts the monocyte-mediated differentiation of T cells to a T helper (Th)-22 phenotype, which may protect from autoimmunity." (PMID 28666018, 2017). "Smoking is an important risk factor for RA; and nicotine exerts effects via Th17 cells; Aryl-hydrocarbon Receptor (AhR) binding by aromatic hydrocarbons and non-halogenated polycyclic aromatic hydrocarbons favors differentiation of Th17 cells and can exacerbate autoimmunity." (PMID 25196523, 2014).
chronic kidney disease (62 papers, 2011 to 2026). Impairment of the renal function secondary to chronic kidney damage persisting for three or more months. "It has been demonstrated that AhR is more stimulated in stage 3 chronic kidney disease patients, directly associated with higher IS levels and inversely proportional to epidermal growth factor receptor (EGFR) levels." (PMID 38592263, 2024). "Most cardiovascular complications associated with chronic kidney disease are secondary to the activation of prooxidative/inflammatory pathways through human AhR activation." (PMID 38592263, 2024). "Many authors have reported that AhR is associated with chronic kidney disease and its complications." (PMID 35743162, 2022). "Circulating p-cresol sulfate and indoxyl sulfate can activate AhR-linked signaling in renal cells, leading to oxidative and inflammatory stress during acute renal injuries or chronic kidney diseases." (PMID 35401522, 2022). "As mentioned in the introduction, exposure to IS activates AhR-linked signaling which mediates oxidative and pro-inflammatory stress in patients with acute renal injuries or chronic kidney diseases." (PMID 35401522, 2022). "Cardiovascular complications observed in chronic kidney disease (CKD) are associated with aryl hydrocarbon receptor (AhR) activation by tryptophan-derived uremic toxins—mainly indoxyl sulfate (IS)." (PMID 32260098, 2020). "Tryptophan metabolite-derived indoxyl sulfate (IS) is identified as one of the uremic toxins and physiological endogenous ligand/activator of aryl hydrocarbon receptor (AHR), associated with atherosclerosis in chronic kidney disease (CKD) patients." (PMID 31885805, 2019). "AHR activity is strongly implicated throughout the course of chronic kidney disease (CKD)." (PMID 35237156, 2022). "Of relevance are studies linking AHR genetic polymorphisms to tobacco-smoke–induced decreases in birth weight, along with associated microalbuminuria, proteinuria, and heightened risk of end-stage renal disease." (PMID 21803694, 2011). "Recent studies have indicated that AhR activation by the accumulation of uremic toxins may be implicated in various kidney diseases, including chronic kidney disease (CKD), CKD-associated complications, diabetic nephropathy (DN), acute kidney injury (AKI) and systemic lupus erythematosus (SLE)." (PMID 38491448, 2024). "Many studies have shown that AhR is associated with chronic kidney disease (CKD) and its complications." (PMID 33415104, 2020). "And it has been shown that tryptophan metabolites play a key role in chronic kidney disease by regulating the AHR signaling pathway." (PMID 40371325, 2025). "Even though the involvement of mTOR and AhR signaling pathways in the development of chronic kidney diseases has been well-established, the potential of α-MT as a modulator of these pathways in the treatment of DN has not been investigated." (PMID 39902076, 2024). "Indoxyl sulfate (IS, one of microbiota-derived toxins) was demonstrated to regulate hepatic P-gp (ABCB1) via AhR in rodent and cell culture models of chronic kidney disease (CKD)." (PMID 39713147, 2024). "Excessive accumulation of indoxyl-3-sulfate and indoxyl sulfate in chronic kidney disease, and elevated levels of kynurenine in acute ischemic stroke, have been reported to promote astrocyte activation via AhR activation." (PMID 38976012, 2024). "In mice with chronic kidney disease, the degree of aryl hydrocarbon receptor activation and uremic metabolite accumulation drives muscle mitochondrial dysfunction via PDK4 upregulation, which decreases mitochondrial pyruvate oxidation." (PMID 38652558, 2024). "This review focuses on summarizing recent findings on the role of AhR activation induced by uremic toxins in chronic kidney disease, diabetic nephropathy and acute kidney injury." (PMID 38491448, 2024).